CDK1 (cyclin dependent kinase 1)
Diseases named in the same sentence as CDK1 in open-access papers (continued):
Sharing a sentence is not in itself a finding about the gene and the disease.
prostate carcinoma (continued). "Despite the negative regulatory effects of CDKN3 on CDK1 and CDK2, an oncogenic role for aberrant overexpression of CDKN3 has been implicated in numerous types of human cancer, including prostate cancer, gastric cancer, nasopharyngeal carcinoma, and esophageal cancer." (PMID 33468140, 2021). "Finally, GSEA revealed that CDK1 expression was involved in prostate cancer, small cell lung cancer, and GC and was significantly correlated with the WNT signaling pathway and T cell receptor signaling pathway." (PMID 33365314, 2020). "In addition, matrine, the main active compound of CKI has been found to exhibit time-dependent inhibition of the expression of CDK1 in prostate cancer cells." (PMID 31275410, 2019). "Our previous studies revealed that tumor-suppressive miR-145-3p was closely involved in human cancer pathogenesis by targeting oncogenes, for example, MTDH in LUSQ; MELK, NCAPG, BUB1, and CDK1 in prostate cancer; MYO1B in head and neck cancer; and MYO1B and DHRS2 in esophageal cancer." (PMID 31514295, 2019). "However, in prostate cancer, CDK1 showed a significant difference between TCGA (Rank 27) and CCLE (Rank 2), showing the different expression patterns between prostate cancer samples and cell lines." (PMID 31277321, 2019). "Further studies of the mechanisms by which Cdk1 and Cdk2 are involved in the plasticity of prostate cancer cells are necessary based on the fact that different approaches to the modulation of their expression and activity were not uniformly reflected in terms of NED promotion." (PMID 24884804, 2014). "Notably, treatment with dichloromethane and ethyl acetate extracts of V. doniana normalised cdk1 expression in DU-145 cancer cells, suggesting these extracts may restore cdk1’s function and mitigate prostate cancer progression." (PMID 39624842, 2024). "In prostate cancer cells, a decrease in its expression promotes the expression of proliferation-related genes MELK, NCAPG, BUB1, and CDK1, thereby promoting cell proliferation." (PMID 41546098, 2026). "In the current study, we showed the suppression of CDK1 and p‐CDK1 (at S308 site) and thereby, it confirms the inhibition effects of green tea extract on PC3 prostate cancer cells through suppression of cell proliferation." (PMID 40336533, 2025). "Cyclin-dependent kinase 1 (CDK1), a crucial cell cycle regulator, is elevated in liver, colorectal, and prostate cancers." (PMID 39859485, 2025). "NANOG, a homeobox TF, is also a biomarker of tumor pluripotency in various cancers, such as ovarian, breast, and prostate cancers, with NANOG stability being assured through phosphorylation by ERK and cyclin-dependent kinase 1 (CDK1)." (PMID 39860065, 2025). "We also investigate the maximum vital goals in prostate cancer therapy such as AR, prostate specific antigen (PSA), AKT, cyclin B1, cyclin dependent kinase (CDK1), phospho‐androgen receptor (p‐AR), and phospho‐CDK1 (p‐CDK1: T161) expression." (PMID 40336533, 2025). "In prostate cancer, SLC14A1 downregulation enhances CDK1/CCNB1 and mTOR pathway activity, accelerating tumorigenesis." (PMID 40746552, 2025). "ATR inhibition can also inflame the TME in the absence of DNA-damaging agents, such as through the direct activation of a CDK1 axis, leading to SPOP-dependent PDL1 degradation in prostate cancer cell lines." (PMID 38473997, 2024). "In prostate cancer, SOX2 dysregulates the cell cycle via upregulating WEE1 and CDK1, resulting in the insensitivity of prostate cancer to NHRSI." (PMID 38331879, 2024). "Simvastatin and lovastatin suppressed expression of CDK1, CDK2, CDK3, CDK4, and CDK6 in prostate cancer cells with reduced cell viability due to induced apoptosis and cell cycle arrest." (PMID 36946734, 2023). "FOXM1 and CDK1 from the KEGG Senescence pathway and EGFR from the Prostate Cancer Pathway are also involved in the DNA repair process." (PMID 35205253, 2022).
prostate carcinoma (continued). "A recent report also showed that ATR inhibits CDK1-SPOP signaling and thus enhances anti-PD-L1 cytotoxicity in prostate cancer." (PMID 36090896, 2022). "pS81 is co‐stimulated by CDK1 and CDK9, both representing potential therapeutic targets in castration‐resistant prostate cancer patients, either alone or in conjunction with direct AR antagonists." (PMID 33932081, 2021). "We found that inhibition of CDK1 expression was followed by a significant blockade of the ability of ABCC5 to proliferate and migrate in prostate cancer." (PMID 33994848, 2021). "In solid tumors, miR-181a has been described to play an important role in cancer progression, i.e., augmented miR-181a expression promotes prostate cancer cell proliferation by down-regulating DAX-1 expression and up-regulating PSA, CDK1, and CDK2." (PMID 32932883, 2020). "In the detailed expression of each prostate cancer sample and cell line, NCI-H660 showed the highest expression of CDK1." (PMID 31277321, 2019). "In prostate cancer PC-3 cells, silencing ANO1 reduced the expression of cyclin D1 (CCND1), cyclin A2 (CCNA2), CDK1 and CDK2." (PMID 27732935, 2016). "In summary, these results showed that deregulation of the cell cycle by inhibition of the activity of the upstream signaling molecules Cdk1 and Cdk2 is at least partly involved in NED modulation in AR-positive prostate cancer cell lines LNCaP and LAPC-4." (PMID 24884804, 2014). "We analyzed 14 additional genes, including the AR-activated genes PSA, FKBP51, ORM1, STAG, Nkx3.1, FASN, AQP3, KLK2, and UGT2B; the AR-repressed genes DKK and FST; and the castration-resistant prostate cancer AR-regulated genes CDC20, CDK1, and UBE2C." (PMID 22761715, 2012). "Our study may also prompt investigators to look deeper into select kinases that phosphorylate AR, such as CDK1/5/9, ACK1, SRC, MAPK, as inhibition of these kinases in AR+ prostate cancers may provide patient benefit in combination with AR-targeted agents." (PMID 37456235, 2023). "In prostate cancer, ABCC5‐bound CDK1 has been found to directly phosphorylate the AR transcription factor to stimulate its activity, further highlighting that CDK1 might possess non‐mitotic transcriptional roles in different cellular contexts." (PMID 37718413, 2023). "Increased CDK1 expression has not been correlated with disease progression in prostate cancer, and we show that its elevated expression increases the likelihood of prostate cancer recurrence." (PMID 26824323, 2016). "However, based on our observations, it is important to consider the possible effects of Cdk1 and Cdk2 inhibition in NED promotion in prostate cancer cells." (PMID 24884804, 2014). "Based on a RAD001-resistant prostate cancer cell line, we recently reported that drug non-responsiveness is characterised by an increased level of cdk1 and cyclin B, which counteracts growth-blocking effects of this drug." (PMID 22782340, 2012). "Nevertheless, the impact that restricting CDK1 activity during S phase might have in the malignant phenotype of prostate cancer has not been addressed." (PMID 36230876, 2022). "Since experiments for elucidating the involvement of Cdk1 and Cdk2 in promoting NED were performed only in AR-positive prostate cancer cell lines, investigating the AR-negative cell lines might shed more light in proposed role of Cdk1 and Cdk2 deregulation in promoting NED." (PMID 24884804, 2014).
prostate carcinoma (continued). "However, a recent publication points to the accumulation of CDK1 and CDK2 in RAD001-resistant prostate cancer cells, which supports our hypothesis that the reduction of α5 evoked by long-term RAD001 exposure may cause an increase in tumour growth." (PMID 22782340, 2012). "We had previously observed that NU6102 inhibited CDK1-dependent nucleolin phosphorylation and CDK2-dependent pRb phosphorylation with equal efficiency in MCF7 cells, and other studies show that 8 μM NU6102 inhibited CDK1-dependent phosphorylation in prostate cancer cells." (PMID 20010939, 2010). "We report that apigenin affects prostate cancer cells at G2 phase rather than at M phase with concomitant down-regulation of the regulators that govern G2-M transition at the transcriptional level including CDK1, CyclinB1, Polo-like kinase 1 (PLK1) and Aurora A." (PMID 35670862, 2022). "Since knocking down cdk1, cyclin B, or Raptor led to a significant reduction of tumor growth in the present study, it seems likely that diminishing these proteins may constitute a crucial mechanism (among others) explaining how VPA slows down the proliferative activity of prostate cancer cells." (PMID 31010254, 2019).
melanoma (85 papers, 2008 to 2025). A malignant, usually aggressive tumor composed of atypical, neoplastic melanocytes. "CDK2 induces resistance to BRAF and hsp90 inhibitors and a high ratio of CDK1 expression leads to resistance of melanoma patients to therapeutic agents which causes a significant decrease in OS." (PMID 39820173, 2025). "The early stage of regeneration (1dpa) and melanoma is characterized by the upregulation of genes, including cdk2, mcm7, pcna, mki67, and cdk1, associated with proliferation and cell cycle." (PMID 38020918, 2023). "As reported by Darbon and co-workers (2000), G2/M arrest in human melanoma cells was associated with impaired dephosphorylation of Cdk1 and checkpoint kinase Chk2 activation." (PMID 37687080, 2023). "The high expression of MHC I in melanoma, colon cancer, and pancreatic cancer is associated with CDK1 upregulation." (PMID 30841635, 2019). "Additionally, our examination showed that CDK2, GSK3B, CSNK2A1, and CDK1 were the significant kinases that target the greatest number of genes associated with metastatic-melanoma." (PMID 39820173, 2025). "The tumor-inhibiting functions of CCT3 silencing in melanoma were associated with CDK1 downregulation in the cell cycle signaling pathway, which might provide novel markers and targets for melanoma diagnosis and treatment." (PMID 35399722, 2022). "For example, CDK1 was associated with tumor initiation in human melanoma via interacting with SOX2." (PMID 34950739, 2021). "In vivo, pharmacological inhibition of the CCNB1/Cyclin-dependent kinase 1 (CDK1) complex with RO-3306 significantly suppressed melanoma growth by enhancing NK cell infiltration and IFN-γ production." (PMID 40430484, 2025). "These dual effects suggest that CCNB1/CDK1 is a promising therapeutic target in melanoma and warrants further investigation." (PMID 40430484, 2025). "This study highlights the critical role of CCNB1/CDK1 in melanoma resistance to NK cell-mediated cytotoxicity and tumor invasiveness." (PMID 40430484, 2025). "In vitro, we confirmed that the CCNB1/CDK1 inhibitor RO-3306 suppresses melanoma growth while boosting NK cell infiltration and activation." (PMID 40430484, 2025). "Specifically, the UALCAN database suggested that CDK1 was significantly upregulated in metastatic melanoma compared with primary melanoma and that high expression of CDK1 was positively correlated with poor prognosis." (PMID 39553047, 2024). "We therefore further researched the CDK1 gene, which is specifically involved in the metastasis process of melanoma and predicts a bad prognosis." (PMID 35906389, 2022). "Phosphorylation of human SOX2 by CDK1 at S249-S250-S251 enhances its nuclear localization and transcriptional activity in melanoma cells." (PMID 35944584, 2022). "UALCAN suggested that CDK1 was significantly upregulated in metastatic melanoma compared with primary melanoma and that high expression of CDK1 was positively correlated with poor prognosis." (PMID 35906389, 2022). "In advanced gastrointestinal stromal tumors, bladder cancer, non-small cell lung cancer, and melanoma, high CDK1 expression promotes the progression of malignant tumors and exacerbates the degree of proliferation of malignant tumor cells." (PMID 36090896, 2022). "CDK1 was significantly upregulated in metastatic melanoma compared with primary melanoma, and high CDK1 expression was positively correlated with worse overall survival." (PMID 35906389, 2022). "Overall, our findings suggest that CCT3 depletions prohibited melanoma progression by downregulating CDK1 expression and is a potential therapeutic target for melanoma." (PMID 35399722, 2022). "Tumorigenic potential and tumor-initiating capacity are significantly increased in melanoma cells with CDK1 overexpression due to its interaction with the pluripotent stem cell transcription factor Sox2." (PMID 35681641, 2022).
melanoma (continued). "The PCR results indicated that the expression of CDK1 mRNA was successfully rescued after shCCT3 melanoma cells were infected with a CDK1 overexpression lentivirus vector." (PMID 35399722, 2022). "In multivariate analysis, CDK1 showed that HR > 1 and the P value was close to 0.05 (HR = 1.23, 95% CI 0.98–1.55, P = 0.053), suggesting that high CDK1 was correlated with poor prognosis of melanoma." (PMID 35906389, 2022). "In this context, Vitexin increased p21 expression and decreased CDK1 in melanoma cell lines and a mice model, suppressing melanoma cell growth through DNA damage by increasing ROS levels." (PMID 33918290, 2021). "Collectively, in our study, both carotenoid extract and nanoemulsion were effective towards inhibition of melanoma cells A375 via elevating cyclin A and cyclin B expressions and decreasing CDK1 and CDK2 expressions for cell-cycle arrest at the G2/M phase." (PMID 34685938, 2021). "Taken together, DET and DETD-35 induced G2/M phase arrest in A375LM5IF4g/Luc melanoma lung-seeking cells by affecting the cdk1/cyclin B1 complex regulation and G2 to M transition." (PMID 33810045, 2021). "CDK1 has been reported to be upregulated in multiple type tumors such as diffuse large B cell lymphomas and melanomas." (PMID 33259133, 2021). "Our results showed that CRO15 directly decreases MELK kinase activity during in vitro kinase assay but also in intact melanoma cells, as indicated by the inhibition of NF-κB phosphorylation and some mitotic makers, such as Cyclin E, CDK1 or CDK2." (PMID 33431809, 2021). "A wealth of evidence has documented that CDK1 is up-regulated as a host modulator of the cell cycle in melanoma, colon, and pancreatic cancer tissues." (PMID 34895070, 2021). "CDK1 overexpression in melanoma cells increases carcinogenic potential and tumor initiation ability." (PMID 32964032, 2020). "Consistent with other studies, in the present study carvone stimulated the cAMP pathway and increased the phosphorylation of Cdc25B and CDK1 via cAMP in conjunction with decreased proliferation of melanoma cells." (PMID 33171851, 2020). "Consistently with the cell proliferation results, the SQ22536 pretreatment abrogated the carvone-induced phosphorylation of Cdc25B and CDK1 in B16F10 melanoma cells." (PMID 33171851, 2020). "Christopher Marshall’s group earlier reported that ROCK and CDK1 co-operate in tumor progression in melanoma and non-small cell lung cancer, in mice models." (PMID 31488179, 2019). "For example, the expression levels of cyclin B1, the regulatory unit of CDK1/cyclin B1 complex important for the transition of G2/M is known to be higher in late stage melanomas compared to benign nevi." (PMID 30745871, 2019). "We have demonstrated an upregulation of CDK1 in a subpopulation of melanoma and colon cancer cells with high MHC I expression that displayed high tumor initiating potential." (PMID 31080551, 2019).